YY1 (YY1 transcription factor)
Diseases named in the same sentence as YY1 in open-access papers (continued):
Sharing a sentence is not in itself a finding about the gene and the disease.
cancer (continued). "The identification of the repressor protein YY1 as a mediator of protection from cancer susceptibility is a step towards a better understanding of the function of this genomic region." (PMID 21814516, 2011). "YY1 also showed similar features in associating with luminal type cancers and showed a significant association with AP-2α/β." (PMID 20025767, 2009). "This suggests that YY1 may linked to mitochondrial function or energy metabolism in cancer cells, providing new insights into the metabolic mechanisms behind YY1's in GC." (PMID 40088083, 2025). "Several miRNAs have been found to have an association with YY1 expression in cancer." (PMID 38539569, 2024). "Similarly, the transcription factor YY1 has been extensively studied and has been linked to pro-cancer activity in several cases." (PMID 38539569, 2024). "We also present bioinformatic analyses demonstrating the overexpression of LAG-3, YY1, and PD-L1 in various cancers, their associations with immune infiltrates, and the fact that when LAG-3 is hypermethylated in its promoter region it correlates with a better overall survival." (PMID 39796650, 2024). "Moreover, low expression of YY1 was associated with poor outcomes of PC patients and other types of cancers derived from the TCGA and GEO database." (PMID 35183226, 2022). "Recent studies have also implicated YY1 in regulating cell metabolism in cancer." (PMID 35693944, 2022). "Aside from those roles, YY1 is also associated with radioresistance in cancer." (PMID 34834139, 2021). "YY1 has also been associated with the regulation of radioresistance in various cancers." (PMID 34834139, 2021). "Moreover, several studies have shown that YY1 is overexpressed in various cancers, and high levels of YY1 are associated with malignant phenotypes of several cancers, including CRC." (PMID 34485123, 2021). "A specific association of YY1 with different CSC markers has been observed in different types of cancer and could serve as a potential therapeutic approach to suppress the expression of CSCs-related transcription factors." (PMID 32226547, 2020). "Thus, understanding of YY1-RelA complex formation, and its association with different cancers would substantially help in the design of novel and effective therapeutic approaches and drug development." (PMID 31824839, 2019). "However, in certain forms of cancer, YY1 expression shows unfavorable association with tumorigenesis." (PMID 31217904, 2019). "Understanding of such role of YY1 may provide new insights into the abnormal regulation of GC-associated genes and pathways in cancer cells." (PMID 28592880, 2017). "Although YY1 regulates mitochondrial complex I genes, and YY1 deficiency disrupts the structure and function of mitochondria, it is unknown whether YY1 affects MnSOD expression in cancer cells." (PMID 28394354, 2017). "YY1 is an important transcription factor implicated in many cancers and drug resistance." (PMID 29100331, 2017). "YY1 is also considered in association with development of a malignant phenotype in some human cancers, which could indicate metastasis or survival." (PMID 24564526, 2014). "Indeed, the role of YY1 in hematologic malignancies has been implicated in various cancers including AML, in which ectopic YY1 expression can contribute to AML malignancy by interfering with the normal myeloid differentiation program." (PMID 25340776, 2014). "We show that the cancer risk-associated allele of rs378854 decreases binding of the transcription factor YY1, activates in vitro expression of reporter constructs relative to the non-risk allele, and increases expression of PVT1 in primary normal human prostate tissue." (PMID 21814516, 2011). "Because of its role in chromatin remodelling, involving interaction with histone-deacetylase (HDAC), YY1 may be associated with global gene expression and has received interest as a potential therapeutic target in human cancer." (PMID 20025767, 2009).
cancer (continued). "Multiple studies have implicated YY1 in the development and progression of cancer." (PMID 19566924, 2009). "Notably, some studies have linked YY1 to the stemness characteristics of cancer stem cells." (PMID 40374599, 2025). "However, according to the results of this study, the OPB and YPB peptides may also cause aberrant oligomerization of YY1, which is generally overexpressed in cancer cells, leading to apoptotic cell death." (PMID 35406384, 2022). "Additionally, YY1 mutation or dysregulation may bring to either its downregulation or overexpression, and the alteration in YY1 intracellular levels may be linked with a wide range of conditions, including cancer." (PMID 32899428, 2020). "However, the mechanisms underlying YY1 expression in these various cancers are unclear." (PMID 28412749, 2017). "Also transcription factor YY1 has been associated with metastatic potential in several cancers." (PMID 19116006, 2008). "This emphasizes the need for additional co‐targets, such as YY1, to facilitate more effective cancer reversion." (PMID 39840939, 2025). "Collectively, YY1 serves as a central hub coordinating drug resistance mechanisms, making its therapeutic targeting a compelling strategy against refractory cancers." (PMID 40867514, 2025). "In contrast, YY1 is frequently overexpressed in most cancers, acting as an oncogene that promotes epithelial-mesenchymal transition (EMT) and metastasis, enhances cancer cell proliferation and survival, and sustains resistance to therapies." (PMID 41327312, 2025). "Among the transcriptional regulators involved, YY1 has emerged as a modulator of CSC-associated phenotypes and drug resistance across multiple cancer types." (PMID 40867514, 2025). "Elucidating YY1’s role in maintaining CSCs and mediating resistance mechanisms provides promising avenues for enhanced cancer therapy." (PMID 40867514, 2025). "The transcription factor YY1 regulates the expression of various genes in malignant tumors by mediating enhancer-promoter interactions." (PMID 40021626, 2025). "Collectively, RKIP and YY1 help define the immune landscape across a broad spectrum of pathological conditions, including cancer, autoimmunity, and metabolic diseases, highlighting the importance of their coordinated regulation." (PMID 41459495, 2025). "Despite compelling evidence of YY1 promoting aggressive cancer behavior, its prognostic significance remains controversial." (PMID 41009346, 2025). "The role of YY1 in cancer has been widely studied, and YY1 overexpression has been reported in malignant tissues and is linked to invasion, metastasis, and poor prognosis across multiple cancer types." (PMID 40867231, 2025). "Pharmacologic targeting of this axis, for example, by enhancing RKIP activity or inhibiting YY1, has shown promise in reversing immune resistance and promoting apoptosis in cancer models." (PMID 41459495, 2025). "YY1 is also often overexpressed in various cancers, and high YY1 expression is correlated with poor prognosis." (PMID 39747661, 2025). "We further checked the effect of erastin on the expression of these genes, and only the mRNA of YY1 was upregulated in erastin-induced cancer cells." (PMID 39800682, 2025). "Collectively, these findings underscore the central role of YY1 as a pivotal transcriptional regulator that bridges apoptotic resistance, cancer progression, and treatment failure." (PMID 40867514, 2025). "In opposition to RKIP, YY1 commonly functions as a suppressor of apoptosis in cancer by upregulating anti-apoptotic genes." (PMID 41327312, 2025). "Mechanistically, YY1 mediates resistance through various mechanisms, including dysregulated signaling pathways, such as DNA repair modulation, drug efflux activation, cancer stemness maintenance, and apoptosis regulation." (PMID 40867514, 2025). "In cancer cells, YY1 modulates immune resistance by enhancing PD-L1 expression and promotes cancer metastasis." (PMID 40416970, 2025).
cancer (continued). "The YY1-RKIP cross talk represents more than a simple antagonistic interaction- it is a regulatory axis central to cancer progression and therapeutic response." (PMID 41327312, 2025). "FEN1 plays a crucial role in DNA replication and repair meaning inhibition of YY1 contributes to making cancer cells more resistant to chemotherapy." (PMID 41327312, 2025). "This study reveals a novel transcriptional antagonism mechanism affecting lnc-FANCI-2 and other cancer-related genes, highlighting YY1 and TFAP2 as potential therapeutic targets in HPV-driven carcinogenesis." (PMID 40953061, 2025). "YY1 has been reported not only as a driver of many cancers, but also as a transcription factor regulating systemic inflammation." (PMID 40668819, 2025). "Chromatin structural regulators, such as CCCTC-binding factor (CTCF) and Yin Yang 1 (YY1), have emerged as critical players in cancer biology." (PMID 40565099, 2025). "YY1 is known to be positively regulated by NF-κB, a transcription factor involved in inflammation, cancer progression, and treatment resistance." (PMID 41327312, 2025). "In urothelial bladder cancer cells, CAFs drive the production of miR-146–5p which can further amplify YY1 expression and promote the activation of cancer stem cell markers such as SOX2, KLF4, ALDH1A1, NANOG, or OCT4." (PMID 41327312, 2025). "Recent studies have identified the Raf kinase inhibitor protein (RKIP) and Yin Yang 1 (YY1) as significant players in cancer biology, exerting opposing effects." (PMID 41327312, 2025). "To better understand the broader relevance of YY1 in oncogenesis, we conducted a comprehensive pan-cancer analysis to evaluate gene expression across multiple cancer types." (PMID 41009346, 2025). "Studies have also found that YY1 (Yin and Yang 1 Protein) plays a promoting role in the occurrence and development of various cancers, while HMCES is a protein related to DNA repair." (PMID 41231037, 2025). "This leads to increased histone H3K18 lactylation (H3K18la), establishing a YY1–lactate–H3K18la positive loop, ultimately leading to cancer cell resistance to cisplatin." (PMID 40867514, 2025). "Despite their distinct molecular mechanisms, mounting evidence has revealed an inverse regulatory relationship between RKIP and YY1, underscoring their critical roles in cancer progression, immune modulation, and therapeutic resistance." (PMID 41327312, 2025). "Previous studies have established YY1’s role in regulating VEGF in multiple types of cancers either directly or indirectly." (PMID 41327312, 2025). "Various strategies are proposed to selectively target YY1 in human cancers and present a promising novel therapeutic approach for treating unresponsive cancer phenotypes." (PMID 38539569, 2024). "The consequences of YY1 overexpression in various cancers are still being explored and its many oncogenic and immune-suppressive properties make it a promising potential therapeutic target." (PMID 38539569, 2024). "Mechanistically, it is shown that YY1 signaling upregulates IL32 secretion in PCs, subsequently activating the β5‐integrin‐Src‐Akt pathway in EGFR‐mutated cancer cells, contributing to their TKI sensitivity." (PMID 39435643, 2024). "The dysregulated NF-κB/Snail/YY1/RKIP loop in cancer, as well as YY1’s potential as a therapeutic target, is examined, presenting inhibitors such as miRNAs, betulinic acid, and NO donors." (PMID 38893192, 2024). "Of primary concern is the potential dual nature of YY1 in GBM cancer cell subsets, acting as both a transcriptional repressor and activator." (PMID 38893192, 2024). "YY1 overexpression has been determined to activate several signaling pathways as observed in several cancers." (PMID 38539569, 2024). "YY1 is a transcription factor widely expressed in human cells and it assumes multiple functions in gene expression regulation and cancer progression." (PMID 38869071, 2024).
cancer (continued). "Targeted therapies against YAP/YY1 show potential in improving clinical outcomes for cancer patients." (PMID 38314086, 2024). "Research investigation on YY1 has shown its importance in various cancer pathways, and many different possible treatment methods." (PMID 39796650, 2024). "Several other miRNAs, as well as regulation mediated by lncRNA, can target YY1 in various cancer types; however, although promising results have been obtained from preclinical studies, there are currently no clinical trials." (PMID 38339244, 2024). "Taken together, our study revealed a synergistic regulatory effect of KDM5C and YY1 on cancer cell proliferation and cell cycle progression." (PMID 39433896, 2024). "The results of the MS analysis indicated that a number of proteins potentially interact with KDM5C, including YY1, the overexpression of which has been observed in the vast majority of cancers." (PMID 39433896, 2024). "YY1 is frequently overexpressed in many cancer types and reshapes the oncogenic gene expression network." (PMID 39433896, 2024). "YY1 is highly expressed in numerous cancer types, and increased levels correlate with poor clinical outcomes." (PMID 38339244, 2024). "The discussion highlights the clinical significance of targeting YY1 and anti-apoptotic proteins in cancer treatment, emphasizing the need for further research to validate clinical applications and identify relevant biomarkers for patient subgroups." (PMID 38893192, 2024). "Supporting evidence suggests a direct correlation between quercetin's binding affinity to various biomolecules implicated in cancer progression, such as NF-κB, COX enzymes, YY1, and DNA, and its potent cytotoxicity against a broad range of cancer cell lines." (PMID 39449919, 2024). "It is found that YY1 transcriptionally upregulates IL‐32 secretion in pericytes, which binds to and activates β5‐integrin in cancer cells, triggering the Src‐Akt signaling pathway and reducing TKI sensitivity." (PMID 39435643, 2024). "The context-dependent function and effects of YY1 in various cancers complicate the design of inhibitors that can selectively target its oncogenic functions without disrupting its physiological role." (PMID 38893192, 2024). "NO is also known to play a role in the NF-κB/SNAIL/YY1/RKIP/PTEN loop in cancer cells through the repression of SNAIL." (PMID 38539569, 2024). "YY1 is upregulated in various cancers, including breast, bladder, cervical, colon, esophageal, liver, brain, and gastric cancers." (PMID 39796650, 2024). "Cho and Bonavida discussed the role of EMT in cancer metastasis and growth with a focus on the role of YY1 in regulating EMT." (PMID 38893192, 2024). "We have performed bioinformatic analyses to further explore the relationship between both YY1 and PD-L1 in cancer and to corroborate these findings." (PMID 38539569, 2024). "In this review, we discuss the regulation of LAG-3 by YY1 as proof of principle for the potential use of targeting YY1 as an alternative therapeutic approach to preventing the immune evasion of cancer." (PMID 39796650, 2024). "MYC was also proposed to cooperate with EZH2 or YY1 to repress the transcription of onco-suppressor genes in cancer while cooperating with YAP/TAZ mainly to enhance the transcription of oncogenes." (PMID 39455556, 2024). "Overall, the upregulation of PD-L1 expression via YY1 through transcriptional, post-transcriptional, epigenetic, and post-translational regulation likely enhances the immune evasion of cancer cells." (PMID 38539569, 2024). "Considering the definition of synthetic lethality and the results presented here, we propose that KDM5C and YY1 form a synthetically lethal gene pair, providing a rationale for the clinical treatment of patients with KDM5C-deficient cancer by targeting YY1." (PMID 39433896, 2024).
cancer (continued). "YY1 over-expression has also been previously reported ex vivo in different cancer types, including those of the breast, bladder, prostate, gastrointestinal, ovaries, esophagus, nervous system, pancreas, and skin." (PMID 37894300, 2023). "The expression of YY1 can lead to numerous effects due to its role in the stability and expression of cancer-related genes." (PMID 37686541, 2023). "Our results reveal a strong inducing (activating) effect of YY1 mRNA expression on cell cycle (31%), apoptosis (16%), and DNA damage (16%) pathways, pan-cancer." (PMID 37894300, 2023). "One study showed that HIF-1α is stabilized by YY1, and the silencing of YY1 reduced cancer progression under hypoxic conditions." (PMID 37686541, 2023). "As a common transcription factor, YY1 has been reported to widely influence gene transcription in various kinds of cancers." (PMID 36195720, 2023). "YY1 plays a crucial role in neurodevelopment, Parkinson’s disease, Alzheimer’s disease, oxidant stress, inflammation, ischemic damage and various cancers (breast cancer, pancreatic cancer, lung adenocarcinoma and colon cancer)." (PMID 36837850, 2023). "One factor controlling the resistance in cancer cells is the gene regulator or transcription factor (TF) Yin Yang 1 (YY1)." (PMID 37686541, 2023). "Indirectly inhibited the downstream target miR-378a-3p and increased YY1 expression to promote cancer progression." (PMID 37901333, 2023). "YY1 is widely recognized as an intrinsically disordered transcription factor that plays a role in development of many cancers." (PMID 37686614, 2023). "In examining YY1 expression in various types of cancer, many studies have indicated an increased level of YY1 expression in patient samples in contrast to normal samples." (PMID 37686541, 2023). "The CCK-8, colony formation and transwell assays all showed that YY1 presence promoted the viability, proliferation and migration activity of cancer cells, while the inhibition of YY1 resulted in the opposite outcome." (PMID 37724907, 2023). "We believe there exists another indirect relationship between RKIP and PTEN because PTEN expression is low in the majority of cancers, in part by NF-κB and YY1." (PMID 37205308, 2023). "The CRISPR/Cas-9-mediated knockout or the novel Inh-YY1 are both promising in their abilities to achieve sensitivity to cancer drug therapy." (PMID 37686541, 2023). "The transcription factor YY1 itself is classified as an oncogene and is upregulated in cancer cells." (PMID 37686541, 2023). "Considering the differences, further therapeutic strategies can be selected based on the background expression levels of CTBP1 and YY1 in different cancer types." (PMID 37240137, 2023). "Due to the role of YY1 as a key regulator in cellular processes, such as survival, proliferation, invasion and metastasis, it plays a large role in the drug-resistance of cancer cell lines." (PMID 37686541, 2023). "In the majority of cancer cells, Snail is overexpressed in part as a result of NF-κB hyperactivation and YY1 overexpression." (PMID 37205308, 2023). "In parallel, the majority of resistant cancers have been reported to overexpress a transcription factor, Yin Yang 1 (YY1), which regulates the chemo-immuno-resistance of cancer cells to therapeutic anticancer cytotoxic agents." (PMID 37686541, 2023). "High levels of YY1 were detected in resistant cancer cells, while the inhibition restored sensitivities to cytotoxic therapies." (PMID 37686541, 2023). "The introduction of guide RNAs (gRNAs), designed to directly target the YY1 gene in cancer cells, is a promising new therapy." (PMID 37686541, 2023). "Recent perspectives have focused on targeting both YY1 and these anti-apoptotic proteins in order to reverse cancer resistance." (PMID 37686541, 2023).